RNU6-31P (RNA, U6 small nuclear 31, pseudogene)
Synonyms: RNU6-31; RNU6-6
Gene: Small nuclear RNA gene on chromosome 2 (200,830,009 to 200,830,116, forward strand). Ensembl gene ENSG00000207116.
Homologues: Orthologues: chimpanzee U6 (99% identical), mouse Gm22307 (97% identical), pig U6 (95% identical), guinea pig U6 (88% identical). Paralogues in human: RNU6-12P (97% identical), RNU6-13P (97% identical), RNU6-32P (97% identical), RNU6-1 (96% identical), RNU6-15P (96% identical), RNU6-17P (96% identical), RNU6-18P (96% identical), RNU6-19P (96% identical), RNU6-2 (96% identical), RNU6-3P (96% identical), RNU6-4P (96% identical), RNU6-5P (96% identical), and 1286 more.